LRRK2 (leucine rich repeat kinase 2)
Diseases named in the same sentence as LRRK2 in open-access papers (continued):
Sharing a sentence is not in itself a finding about the gene and the disease.
Parkinson disease (continued). "The known expression of leucine-rich repeat kinase 2 in immune cells and its negative regulatory function of nuclear factor of activated T cells implicates leucine-rich repeat kinase 2 in the development of the inflammatory environment characteristic of Parkinson’s disease." (PMID 28649611, 2017). "Besides CD and leprosy, LRRK2 is also involved in Parkinson’s disease." (PMID 27830463, 2017). "Therefore, Ser(P)- 1292 LRRK2 may be a useful candidate biomarker for further exploration of Parkinson's disease." (PMID 28912682, 2017). "Thus, LRRK2 kinase inhibitors are in development as potential Parkinson’s disease therapeutics." (PMID 27503089, 2016). "We recently measured HSPA8 in cerebrospinal fluid (CSF) samples from patients with sporadic Parkinson’s disease (PD), PD patients carrying leucine-rich repeat kinase 2 (LRRK2) gene mutations, healthy control subjects carrying LRRK2 mutations, and healthy controls without LRRK2 mutations." (PMID 27507943, 2016). "Alcalay and colleagues reported that the LRRK2 G2019S mutation was associated with the postural instability and gait dysfunction dominant (PIGD) phenotype rather than the tremor dominant (TD) phenotype in early onset PD based on the Unified Parkinson’s Disease Rating Scale (UPDRS)." (PMID 27330837, 2016). "Further work also showed the mitochondrial respiratory chain was rescued in LRRK2-mutant fibroblasts, thereby widening the potential of this small molecule compound to provide some level of compensation for the mitochondrial dysfunction seen in multiple subtypes of Parkinson's disease." (PMID 24750211, 2015). "Moreover, multiple system atrophy (MSA) is characterized clinically by parkinsonism, however, p.G2019S mutation in the LRRK2 gene is unlikely to be associated with MSA." (PMID 25391693, 2014). "Defective microtubule-based axonal transport is hypothesized to contribute to Parkinson’s disease, but whether LRRK2 mutations affect this process to mediate pathogenesis is not known." (PMID 25316291, 2014). "However, although the common G2019S mutation has been reproducibly shown to elicit increased LRRK2 kinase activity this mutation appears unique: all other mutations segregating with Parkinson’s disease have no reproducible effect on kinase activity." (PMID 23754980, 2013). "The lentiviral approach used in the present study could similarly be used to examine the effects of aging on the toxicity of mutant proteins involved in other neurodegenerative diseases (e.g. PS1/APP for Alzheimer's disease, and DJ-1, PINK-1, and LRRK2 for Parkinson's disease)." (PMID 19247483, 2009). "While acknowledging that LRRK2-associated parkinsonism without evidence of asyn aggregates is a biologically heterogeneous group, we hypothesized that LRRK2-associated parkinsonism without evidence of asyn aggregates would generally follow a more benign motor course." (PMID 40114783, 2025). "Four well-characterized Parkinson disease genes, SNCA, LRRK2, DNAJC6, and PARKN, are situated within or adjacent to VERT regions." (PMID 40894531, 2025). "The mutants included in this study are ‘classical’ Parkinson disease genes, like LRRK2 and PINK1, and Parkinsonism genes that affect vesicle trafficking processes, including SYNJ1, DNAJC6/Aux. and RAB39B." (PMID 40178224, 2025). "Moving forward, validating whether LRRK2 inhibition can similarly dampen microglial activation in α-syn–driven models will be critical for corroborating our therapeutic strategy.the simplicity of these models limits their ability to recapitulate the complexity of human Parkinson’s disease." (PMID 40169487, 2025).
Parkinson disease (continued). "Those in the LRRK2 and PRKN compound heterozygous/homozygous groups were more likely to have a first-degree relative with Parkinson’s disease (40%, 47% versus 19%; P = 1.11 × 10−11 and 1.36 × 10−6)." (PMID 39074992, 2024). "Similar post-mortem observations have been made in LRRK2 and PINK1 parkinsonism, but further comparisons would be helpful." (PMID 38614108, 2024). "While acknowledging that LRRK2-associated parkinsonism without evidence of asyn aggregates are a biologically heterogeneous group, we hypothesized that LRRK2-associated parkinsonism without evidence of asyn aggregates would generally follow a more benign motor course." (PMID 39108519, 2024). "A long non-coding RNA stimulates the expression of LRRK2, which aids in promoting MPTP-induced parkinsonism." (PMID 38254673, 2024). "There is substantial evidence for a continuum of risk, quantified as altered odds ratio for disease, for several of the genes involved in monogenic Parkinson's disease, such as SNCA, LRRK2 and GBA1 (all with direct or close links to the endo-lysosomal system)." (PMID 38368938, 2024). "This supports the promotion of universal access to genetic testing for Parkinson’s disease, as well as therapeutic trials for GBA1 and LRRK2-related Parkinson’s disease." (PMID 39074992, 2024). "HSP70 activated mitochondrial metabolism and mitophagy that protected rotenone-treated neurons and Parkinson’s disease PINK1 and LRRK2 fibroblasts from cell death." (PMID 38429623, 2024). "For the combination of a protein and the term “AND LRRK2,” we found 57 publications for 22 proteins, all of which were also identified using the “AND Parkinson’s disease” term." (PMID 39726830, 2024). "Leucine-rich repeat kinase 2 (LRRK2), the known mutant gene involved in both familial and sporadic Parkinson’s disease (PD), is a multidomain protein (2527 amino acids, 286 kDa) widely expressed in circulating immune cells, the liver, the kidney and the brain." (PMID 37048114, 2023). "However, in Parkinson’s-related Drosophila model, furin 1 has been found to be highly concentrated in TH-positive DA neurons, and furin 1 is translationally regulated by leucine-rich repeat kinase 2 (LRRK2) and involved in the impairment of synaptic plasticity and neurodegeneration." (PMID 35996194, 2022). "Well-established Parkinson’s disease genes include autosomal dominant forms (SNCA, LRRK2, and VPS35) and autosomal recessive forms (PRKN, PINK1 and DJ1)." (PMID 35328025, 2022). "Galactose induced a modest, but statistically significant, reduction in the mitochondrial aspect ratio only in LRRK2 and PARK2 mutant fibroblasts (left), but provoked mitochondrial depolarization in all three Parkinson’s disease cell lines (right)." (PMID 35326504, 2022). "Inhibition of LRRK2 kinase activity restored defective PINK1 dependent mitophagy in Parkinson’s disease, indicating a link between PINK1 and LRRK2." (PMID 33546409, 2021). "Another powerful example is the use of phosphoproteomics screening analysis of Parkinson disease associated kinase LRRK2, in combination with different pharmacological inhibitors that uncovered Rab GTPases as key LRRK2 substrates, and pointed toward a new disease mechanism in PD." (PMID 33642997, 2021). "In fact, variants at numerous other genetic loci related to endocytic trafficking and synaptic maintenance have been discovered as risk factors for Alzheimer’s disease (BIN1, PICALM, CD2AP, SORL1) and Parkinson’s disease (SNCA, LRRK2, SH3GL2/EndoA, RAB7L1)." (PMID 32286230, 2020). "Among those, a highly specific clone detects pThr73 levels in human peripheral blood cells of (mutant) LRRK2 G2019S and VPS35-D620N carriers with Parkinson's disease." (PMID 32601174, 2020). "Leucine rich repeat kinase 2 (LRKK2), involved in Parkinson’s disease, has a role with ACE2 in the reactive oxygen species metabolic process." (PMID 32268515, 2020).
Parkinson disease (continued). "Treatment with the LRRK2 inhibitor, PFE-360, relieved the phenotype of Parkinson’s disease in midbrain-like simBOs." (PMID 33195269, 2020). "We propose that synergistic LRRK2/IFN-γ activation serves as a potential link between inflammation and neurodegeneration in Parkinson’s disease." (PMID 33057020, 2020). "Although patients carrying mutations in LRRK2 present with a phenotype clinically and pathologically indistinguishable to idiopathic Parkinson's, it is possible that LRRK2 studies might not apply to the whole Parkinson's population." (PMID 29746898, 2018). "The purpose of the present study was to test the practicability of assessing LRRK2-mediated Rab10 phosphorylation in a patient cohort in a clinical setting and not to address whether Rab10 phosphorylation is elevated in patients with Parkinson's or G2019S carriers." (PMID 29127255, 2018). "The LRRK2 gene is a major contributor to genetic risk for Parkinson’s disease and understanding the biology of the leucine-rich repeat kinase 2 (LRRK2, the protein product of this gene) is an important goal in Parkinson’s research." (PMID 29308544, 2018). "Leucine-rich repeat kinase 2 expression was increased in B cells (p = 0.0095), T cells (p = 0.029), and CD16+ monocytes (p = 0.01) of Parkinson’s disease patients compared to healthy controls." (PMID 28649611, 2017). "LRRK2, also known as PARK8, was first discovered in autosomal-dominant, late-onset parkinsonism by genetic linkage analysis in 2002, and two years later, LRRK2 gene was cloned and its related mutations were reported." (PMID 27004687, 2016). "Discoveries of familial PD kinase leucine-rich repeat kinase 2 (LRRK2) protein, α-Synuclein locus duplication, and mouse models of Parkinson’s provide clues for understanding the impact of various signaling events on neurodegeneration." (PMID 27494614, 2016). "The function of LRRK2 in the CNS is not known, but examination of the pathogenic process of Parkinson’s disease revealed the involvement of inflammatory processes in this condition, suggesting that a defect in the lymphoid system could play a role in the pathogenic process of this disease." (PMID 26067490, 2015). "Leucine-rich repeat kinase-2 (LRRK2), a cytoplasmic protein containing both GTP binding and kinase activities, has emerged as a highly promising drug target for Parkinson’s disease (PD)." (PMID 25816252, 2015). "The motor phenotype of LRRK2-PD resembles IPD and is characterized by parkinsonism of late onset that responds to L-Dopa therapy and motor complications of dopaminergic therapy." (PMID 26177462, 2015). "Also, we hypothesized that sleep disorders that are known to occur in premotor IPD may also be present in LRRK2 mutation carriers who have not developed parkinsonism yet." (PMID 26177462, 2015). "The leucine-rich repeat kinase 2 (LRRK2) gene was found to play a role in the pathogenesis of both familial and sporadic Parkinson’s disease (PD)." (PMID 24167564, 2013). "Here, we follow up on those results, screening not only LRRK2, but also PRKN, SNCA and PINK1 in a cohort of early-onset and late-onset familial Portuguese Parkinson disease patients." (PMID 18211709, 2008). "LRRK2 parkinsonism cases without evidence of alpha-synuclein aggregates as a group exhibit less severe motor manifestations and decline." (PMID 40114783, 2025). "The involvement of LRRK2 kinase function in inflammasome activation may provide insight into its role as a driver of gut inflammation in IBD and, by extension, Parkinson’s disease." (PMID 41246319, 2025). "Additionally, multiple Parkinson’s disease-related genes, including VPS35 and LRRK2, also regulate MAPL-induced pyroptosis." (PMID 41083601, 2025).
Parkinson disease (continued). "The LRRK2 WDR domain is an understudieddrug target for Parkinson’s disease, with no known inhibitorsprior to the first phase of the Critical Assessment of ComputationalHit-Finding Experiments (CACHE) Challenge." (PMID 40415386, 2025). "Motivated by this convergence of Parkinson’s disease genes and the fact that activated STING traffics through cellular compartments (Golgi, endosomes, and lysosomes) where LRRK2 has been proposed to function, we investigated the relationship between LRRK2 and STING signaling." (PMID 39812709, 2025). "These technologies, including whole-exome sequencing (WES) and whole-genome sequencing (WGS), have facilitated the identification of pathogenic mutations in genes such as APP, PSEN1, and PSEN2 in Alzheimer’s disease (AD), as well as LRRK2, SNCA, and PINK1 in Parkinson’s disease (PD)." (PMID 40076852, 2025). "Moreover, RPS15 (uS19) can be phosphorylated by leucine-rich repeat kinase 2 (LRRK2), leading to aberrant cap-dependent and cap-independent translation, involved in the aetiology of Parkinson's disease." (PMID 39045153, 2024). "We measured the amount of 91 microRNAs present in blood of individuals with an alteration in the LRRK2 gene and compared their pattern to patients with a non-inherited form of Parkinson’s disease and healthy controls." (PMID 38848197, 2024). "For example, recent evidence suggests that LRRK2, glucocerebrosidase (GBA) and idiopathic PD (iPD) have distinct Parkinson’s disease-related patterns (PDRPs) in network connectivity, which seem to be independently associated with symptom profile and progression." (PMID 38672010, 2024). "We found a female predominance among the LRRK2 parkinsonism cases without evidence for pathologic asyn." (PMID 39108519, 2024). "Further, neuropathologic studies of homozygous LRRK2 G2019S carriers with Parkinson’s disease (PD) are rare, and there are no systematic reports of clinical features in those cases." (PMID 39175765, 2024). "We know that alterations in a gene called Leucine Rich Repeat Kinase 2 are important in both inherited and non-inherited cases of Parkinson’s disease." (PMID 38848197, 2024). "For example, the G2019S mutation has been shown to alter the dynamics of mitochondria in glial cells, and brain lysates from rodent models of Parkinson’s disease demonstrate higher levels of pro-inflammatory factors TNF-α and Drp1, reflecting the role of LRRK2 in neuroinflammation." (PMID 37886972, 2023). "Understanding how PPM1H modulates LRRK2 activity is of fundamental interest and also important, as activators of PPM1H may eventually benefit Parkinson’s disease patients." (PMID 37889931, 2023). "A novel likely pathogenic variant in LRRK2 [MIM: 609007] c.4334C>G (p.Ser1445Cys) was identified in a patient with a European background and non-motor symptoms in Parkinson’s disease and dementia." (PMID 35260199, 2022). "Given the effects of lifestyle and environment on LRRK2 and the protective effects of smoking, caffeine and anti-inflammatory drugs on IPD, there is ongoing interest in AAO, penetrance and other lifestyle factors in LRRK2 parkinsonism." (PMID 38835904, 2022). "At least 19 genetic loci for Parkinsonism have been identified to date, ten of which are autosomal dominant genes: SNCA (PARK1/PARK4), PARK3, UCHL1 (PARK5), LRRK2 (PARK8), GIGYF2 (PARK11), HTRA2 (PARK13), VPS35 (PARK17), EIF4G1 (PARK18), TMEM230 (PARK21), and CHCHD2 (PARK22)." (PMID 34356877, 2021). "Further features differentiating LRRK2 p.G2019S-related Parkinsonism from iPD are the absence of gender differences, the slower progression for motor signs and cognitive impairment, and the more frequent occurrence of postural-instability-gait-difficulty." (PMID 34630269, 2021). "While the clinical presentation of LRRK2 parkinsonism has been largely indistinguishable from sporadic PD, disease penetrance and age at onset can be quite variable." (PMID 33494262, 2021).
Parkinson disease (continued). "In particular, LRRK2-IN-1 (XMD11-50), another creation of the Gray lab, developed to target the key Parkinson’s disease target LRRK2, has been used to study potential effects of DCLK1 kinase inhibition in colorectal cancer, pancreatic cancer, head and neck cancer, and cholangiocarcinoma." (PMID 34830884, 2021). "Leucine-rich repeat kinase 2 (LRRK2) small-molecule kinase inhibitors and anti-sense oligonucleotides have demonstrated neuroprotective efficacy in some models of Parkinson’s disease (PD) and represent a promising novel class of disease-modifying therapeutics for neurodegeneration." (PMID 33298972, 2020). "Although the first reports of LRRK2 mutations were in families with multiple affected members, later studies have shown that a large proportion of LRRK2 carriers do not have other family members affected by Parkinson’s disease." (PMID 31324919, 2019). "One example that parallels our findings for C9ORF72 is the major Parkinson disease gene LRRK2 that is broadly expressed in non-neuronal cells, and even within the nervous system, LRRK2 expression levels are low in the most affected area, the substantia nigra." (PMID 31612854, 2019). "We suggest that LRRK2 should be tested more frequently in young-onset patients, even those without a family history of Parkinson’s disease; however, additional studies in both young-onset and late-onset patients are needed." (PMID 31324919, 2019). "LRRK2 (PARK 8) is hypothesized to play a role upstream of the MAPK pathway and to mediate both familial and sporadic Parkinson’s disease by inducing intrinsic neuronal apoptosis." (PMID 30374342, 2018). "Estimated presence of nonmotor symptoms in LRRK2 G2019S Parkinson’s disease patients and idiopathic Parkinson’s disease patients in relation to onset of motor symptoms." (PMID 25330404, 2014). "The most important and widely accepted monogenically inherited Parkinson's disease genes are α-synuclein (SNCA) and leucine-rich repeat kinase 2 (LRRK2) for late-onset disease and Parkin (PARK2), oncogene DJ1 (DJ1) and PTEN Induced Putative Kinase 1 (PINK1) for early onset." (PMID 24133413, 2013). "As mentioned, LRRK2 parkinsonism cases without evidence of aggregates often exhibit Alzheimer’s disease pathology, and these results could in part be a reflection of sex differences in Alzheimer’s disease." (PMID 40114783, 2025). "Similarly, endocytosis of monomeric tau is dependent on the familial Parkinson’s disease gene LRRK2, but not required for endocytosis of fibrillar tau." (PMID 40790356, 2025). "PD-related genes have been discovered, for example, α-synuclein, Parkin, PINK1 (phosphatase and tensin homologue-induced putative kinase 1), LRRK2 (leucine-rich repeat kinase 2), and DJ-1 (also known as Parkinson disease protein 7 [PARK7])." (PMID 38841098, 2024). "As mentioned, asyn-negative LRRK2 parkinsonism cases often exhibit AD pathology, and these results could in part be a reflection of sex differences in AD." (PMID 39108519, 2024). "LRRK2 parkinsonism cases without evidence of alpha-synuclein aggregates as a group exhibit less severe motor manifestations and decline may have more significant cognitive dysfunction." (PMID 39108519, 2024). "As we know that LRRK2 also plays a role in some patients with a non-inherited form of Parkinson’s disease, this microRNA pattern could maybe even help us to identify these individuals." (PMID 38848197, 2024). "In addition, I will discuss how these models fare with respect to the features of a “gold standard” animal models and what could be attempted in future studies to exploit LRRK2 and GBA1 rodent models in the fight against Parkinson’s disease." (PMID 36085537, 2023). "However, covariants of GBA and LRRK2 combined with hypoxic insults in clinical cases of Parkinsonism have not yet been reported." (PMID 37301871, 2023).